CDK2AP1 (cyclin dependent kinase 2 associated protein 1)
Description:
Inhibitor of cyclin-dependent kinase CDK2 (By similarity). Also acts as a component of the histone deacetylase NuRD complex which participates in the remodeling of chromatin.
Synonyms: DOC-1; DOC1; DORC1; ST19; p12DOC-1
Tractability: Small molecule: it has a binding pocket of medium quality. PROTAC: ubiquitination databases record sites on it; a small molecule that binds it is known.
Gene: Protein-coding gene on chromosome 12 (123,250,112 to 123,272,334, reverse strand). Ensembl gene ENSG00000111328.
Subcellular location: Nucleus; Chromosome
Subcellular location (Human Protein Atlas): Nucleoplasm; Cytosol
Pathways (Reactome):
Chromatin organization: Interaction of NuRD complexes with transcription factors; NuRD complex assembly
Gene Ontology:
Molecular function: DNA polymerase binding; protein binding
Biological process: regulation of transcription by RNA polymerase II; DNA-templated DNA replication
Cellular component: chromatin; chromosome; cytosol; nucleoplasm; nucleus; NuRD complex; perinuclear region of cytoplasm; cytoplasm
Genetic constraint (gnomAD): Loss-of-function variants: 4 observed, 5.83 expected, observed/expected ratio (o/e) 0.69, 90% interval 0.34 to 1.52. That is too few expected variants to judge how well the gene tolerates losing a copy. Missense variants: 32 observed, 59.63 expected, observed/expected ratio (o/e) 0.54, 90% interval 0.4 to 0.72. Synonymous variants: 23 observed, 20.81 expected, observed/expected ratio (o/e) 1.11, 90% interval 0.79 to 1.56.
Homologues: Orthologues: dog CDK2AP1 (97% identical), mouse Cdk2ap1 (97% identical), mouse Cdk2ap1rt (97% identical), pig CDK2AP1 (97% identical), chimpanzee CDK2AP1 (91% identical), macaque CDK2AP1 (90% identical), rat Cdk2ap1 (87% identical), guinea pig CDK2AP1 (84% identical), tropical clawed frog cdk2ap1 (83% identical), zebrafish CDK2AP1 (69% identical), Drosophila melanogaster CDK2AP1 (54% identical), Caenorhabditis elegans Y43F4B.10 (35% identical). Paralogues in human: CDK2AP2 (63% identical).
Diseases named in the same sentence as CDK2AP1 in open-access papers:
CDK2AP1 is named in the same sentence as 32 diseases in open-access papers, as found by Europe PMC text mining. Sharing a sentence is not in itself a finding about the gene and the disease. The quoted sentences say what the papers report.
oral cancer (5 papers, 2009 to 2025). "Accordingly, CDK2AP1 protein-deficient oral cancer cell lines express as much CDK2AP1 mRNA as proficient cell lines." (PMID 37217493, 2023). "Recently, emerging evidence suggests that loss or reduced expression of CDK2AP1 might contribute to the tumorigenesis in many types of malignancies including esophageal carcinoma, oral cancer, prostate cancer, colorectal cancer and gastric cancer." (PMID 26515287, 2015). "CDK2AP1 is a highly conserved and ubiquitously expressed gene located on human chromosome 12q24 and is a 115-aa nuclear polypeptide that is downregulated in ∼70% of oral cancers." (PMID 19229340, 2009). "CDK2AP1 was initially identified as a cancer-related gene by using hamster oral cancer model." (PMID 19229340, 2009). "Here, we focused on the role of CDK2AP1 in modulating the competition between NuRD and SWI/SNF chromatin remodeling complexes in the coordinated regulation of key downstream signaling pathways that underlie phenotypic plasticity during oral cancer progression and metastasis." (PMID 40112045, 2025). "Collectively, these results indicated the central role of BRG1- and CDK2AP1-specific SWI/SNF and NuRD chromatin remodelers in the coordinated deregulation of EMT- and inflammation-related target gene expression in oral cancer cells and inflammation in their microenvironment." (PMID 40112045, 2025).
glioma (4 papers, 2015 to 2022). A benign or malignant brain and spinal cord tumor that arises from glial cells (astrocytes, oligodendrocytes, ependymal cells). "Clinical/radiographic determined glioma grade at reRT time point was associated with differential expression of CDK2AP1 which has been implicated in glioma tumorigenesis (putative tumor suppressor)." (PMID 35158950, 2022). "Although the majority of existing reports support the role of CDK2AP1 to be a tumor suppressor, recent studies have shown that knockdown of CDK2AP1 in human glioma cells reduced proliferation, caused a G0/G1 cell cycle arrest and increased apoptosis." (PMID 25785833, 2015). "Previous studies have demonstrated that CDK2AP1 influence tumor growth such as glioma, lung cancer and esophageal squamous cell carcinoma." (PMID 36105112, 2022). "It was shown that RNAi-mediated knockdown of CDK2AP1 in U251 and U373 human glioma cells resulted in reduction in cell proliferation and arrested cells in G0/G1 phase of the cell cycle." (PMID 25785833, 2015). "Knockdown of CDK2AP1 significantly inhibits glioma cell proliferation and induces cell cycle arrest in G0/G1 phase, thus speculating that CDK2AP1 may be an anti-apoptotic molecular switch in glioma development." (PMID 36105112, 2022).
breast carcinoma (3 papers, 2022 to 2025). "Furthermore, recent studies have shown that the CDK2AP1 protein, through the negative regulation of the CDK2 kinase, acts as a tumor suppressor for breast cancer." (PMID 36765875, 2023).
laryngeal squamous cell carcinoma (3 papers, 2015 to 2023). A squamous cell carcinoma that arises from the larynx. "Two previous studies suggested that noncoding RNAs and in particular microRNAs (miR-21 and miR-205) could underlie the silencing of CDK2AP1 expression in oral and laryngeal squamous cell carcinoma, respectively." (PMID 37217493, 2023). "Two studies have previously suggested the involvement of specific microRNAs, namely miR-21 and miR-205, in the silencing of CDK2AP1 expression in oral and laryngeal squamous cell carcinoma, respectively." (PMID 37217493, 2023).
oral squamous cell carcinoma (3 papers, 2015 to 2025). "While the loss of CDK2AP1 protein expression in oral squamous cell carcinoma has been previously reported, the underlying mechanisms are yet poorly understood." (PMID 37217493, 2023). "A significant correlative expression of TGF-β receptor II (TGFβRII) and CDK2AP1 has been found in human oral squamous cell carcinoma (OSCC) tissues with an observed loss of expression of CDK2AP1 and p21." (PMID 25785833, 2015). "In the normal tongue epithelium, CDK2AP1 expression follows an increasing gradient along the basal–squamous axis (i.e., it increases as cells start differentiating into squamous lineages), and its loss is associated with a substantial proportion of human oral squamous cell carcinomas (OSCCs) cases." (PMID 37217493, 2023). "To further validate the low incidence of CDK2AP1 mutations in oral squamous cell carcinoma, we established a panel of OSCC cell lines shown by western analysis to be either proficient or deficient for CDK2AP1 protein expression." (PMID 37217493, 2023). "A reduction of CDK2AP1 expression is considered to be a negative prognostic indicator in patients with oral squamous cell carcinoma and also associated with increased invasion in human gastric cancer tissue." (PMID 25785833, 2015). "In the vast majority of oral squamous cell carcinomas (OSCC), expression of the CDK2AP1 protein is reduced or lost." (PMID 37217493, 2023).
prostate carcinoma (3 papers, 2015 to 2022). A carcinoma that arises from epithelial cells of the prostate gland. "The effects of overexpressing CDK2AP1 in prostate cancer cell lines, in which it is downregulated were also evaluated." (PMID 25785833, 2015). "Overexpression of CDK2AP1 in prostate cancer cell lines lead to increased apoptosis, growth arrest and reduced invasion." (PMID 25785833, 2015). "CDK2AP1 overexpression was shown to inhibit growth, reduce invasion and increase apoptosis in prostate cancer cell lines." (PMID 25785833, 2015). "Furthermore, it has been described that interleukin-6 is down regulated in human prostatic carcinoma cells which provides further evidence for this enrichment gene analysis and role of CDK2AP1 as an oncogene." (PMID 36362115, 2022). "In vitro studies focused on overexpression of CDK2AP1 in prostate cancer cell lines results in a decrease in levels of CDK2 and its kinase activity, leading to an accumulation of cells in the G1 phase and a reduction in cells that are in the S phase of the cell cycle." (PMID 25785833, 2015).
amyloid (2 papers, 2022 to 2025). "Moreover, the astrocytic cyclin-dependent kinase 2-associated protein 1 (CDK2AP1) has shown a significant association with cognitive function examinations (Mini-Mental state examination test), neurofibrillary tangles and amyloid plaques in human AD studies." (PMID 36362415, 2022). "CDK2AP1 had the strongest association with cognitive measures and NFT burden, and also showed an association with amyloid plaque burden." (PMID 40042520, 2025).
gastric cancer (2 papers, 2015). A primary or metastatic malignant neoplasm involving the stomach. "In gastric cancer, it was found that patients who had higher levels of CDK2AP1 in their samples had a better prognosis than patients who had low levels of CDK2AP1." (PMID 25785833, 2015).
squamous carcinomas (2 papers, 2009 to 2023). "It has been shown that Cdk2ap1 is activated by TGF-β-Smad2 and mediates TGF-β induced growth arrest in normal diploid cells and the loss of Cdk2ap1 expression in squamous cell carcinoma is correlated with disrupted TGF-β-Smad signaling pathway." (PMID 19229340, 2009). "To analyze the clinical relevance of the selected CDK2AP1-antagonist miRs, we interrogated publicly available databases and validated the results by combining miR-FISH and CDK2AP1 IHC on tissue microarrays (TMAs) encompassing oral squamous carcinomas of the tongue." (PMID 37217493, 2023).
hepatocellular carcinoma (1 paper, 2022). A malignant tumor that arises from hepatocytes. "However, to the best of our knowledge, the expression and mechanism of CDK2AP1 in hepatocellular carcinoma have not been reported yet." (PMID 36105112, 2022).
liver cancer (1 paper, 2022). An epithelial or non-epithelial malignant neoplasm that arises from the liver. "Intervention of CDK2AP1 may have obvious benefits on the prognosis of liver cancer patients." (PMID 36105112, 2022).
lung carcinoma (1 paper, 2022). "In lung cancer, however, the antitumor activity of CDK2AP1 may act through affecting cell cycle regulators other than CDK2." (PMID 36105112, 2022).
metastatic disease (1 paper, 2022). "Separately in this cohort, high CDK2AP1 and high AR expression were significantly associated with metastatic disease (p value 0.034 and 0.019, respectively) and when combined, there is a higher rate of metastatic disease observed in high CDK2AP1 and high AR expression cases (p value 0.013)." (PMID 36362115, 2022). "Overall, the higher expression of CDK2AP1 in high Gleason Group and metastatic tumors demonstrate its role as a potential biomarker for lethal PCa." (PMID 36362115, 2022). "Furthermore, there was a significant increase in the mean intensity of CDK2AP1 expression in metastatic disease when compared to non-metastatic disease." (PMID 36362115, 2022).
prostatic adenocarcinoma (1 paper, 2022). "Earlier studies suggest that CKD2AP1 may function as a tumor suppressor, however, we saw a unique CDK2AP1 overexpression pattern in prostatic adenocarcinoma along with most other malignancies." (PMID 36362115, 2022).
rectum adenocarcinoma (1 paper, 2022). An adenocarcinoma arising from the rectum. "The correlation between the expression level of CDK2AP1 and neoantigens was performed, which indicated that CDK2AP1 expression was significant related to neoantigens in GBM (p = 0.019), BRCA (p = 9.2e-06) and rectum adenocarcinoma (READ) (p = 0.00021)." (PMID 36105112, 2022).
tongue tumors (1 paper, 2025). "As previously shown, the majority of tongue tumors show a mixture of CDK2AP1 positive and negative cells, with only a minority of cases demonstrating homogenous loss." (PMID 40112045, 2025).
tumor (19 papers, 2009 to 2025). "Cyclin-dependent kinase 2-associated protein 1 (CDK2AP1) gene is a highly conserved tumor suppressor mapping to chromosome 12q24, originally identified and cloned from the Syrian hamster oral cancer model and named deleted in oral cancer-1 or DOC1." (PMID 37217493, 2023). "Our results reveal that multiple miRNAs contribute to the loss of the tumor suppressor function of CDK2AP1 in OSCC patients in association with poor overall survival." (PMID 37217493, 2023). "Cyclin Dependent Kinase-2 Associated Protein-1 (CDK2AP1) is known to be a tumor suppressor that plays a role in cell cycle regulation by sequestering monomeric CDK2, and targeting it for proteolysis." (PMID 25785833, 2015). "Moreover, by comparing the expression of CDK2AP1 in LIHC samples at different clinical stages and histologic grades, we found that increased expression of CDK2AP1 associated significantly with clinical stage (p < 0.001) and tumor grade (p < 0.001)." (PMID 36105112, 2022). "In addition, we used TIMER and ESTIMATE to explore the association between CDK2AP1 expression and tumor microenvironment related immune cells, stromal cells, and tumor cells." (PMID 36105112, 2022). "The secretome of CDK2AP1-KO tumor cells exhibits an extensive chemoattractant profile for monocytes and underlies the polarization of macrophages toward an M2-like state." (PMID 40112045, 2025). "Increased tumor-forming efficiency was also observed in the parental CA1 line compared to the CDK2AP1-depleted clones (8/8 vs 4/8 upon injection of 5 × 105 cells)." (PMID 40112045, 2025). "This approach highlights not only the inter-tumor heterogeneity but also the different CDK2AP1 and miR-21-5p expression patterns within each core when the microscope image is paired with the digital reconstruction across the TMA core." (PMID 37217493, 2023). "The main tumor suppressive function originally attributed to CDK2AP1/DOC1 lies in its role as a negative regulator of the cell cycle through the inhibition of cyclin-dependent kinase 2 (CDK2) and DNA polymerase alpha/primase during the S-phase." (PMID 37217493, 2023). "To date, which between the cell cycle- and epigenetic-related functions of CDK2AP1 does represent its main tumor-suppressing activity, still remains elusive." (PMID 37217493, 2023). "To further illustrate the role of CDK2AP1 in tumor biological process, we used the Linkedomics database to explore the co-expression pattern of CDK2AP1." (PMID 36105112, 2022). "To further identify potential targets for LIHC tumor immunotherapy, we used RNAseq data from the TCGA database to check the relationship between CDK2AP1 expression and immune-related pathways and checkpoint genes." (PMID 36105112, 2022). "The specific impact mechanism between CDK2AP1 and tumor development is still unclear, and further studies are needed to verify it." (PMID 36105112, 2022). "Afterwards, we discussed the relationship between CDK2AP1 and neoantigens, microsatellite instability (MSI), tumor mutation burden (TMB), and immune infiltration, which is helpful to further explore the immunotherapy of HCC." (PMID 36105112, 2022). "Pan-cancer sequencing data obtained from TCGA database were used to compare CDK2AP1 expression in 20 different types of tumor and corresponding normal tissues." (PMID 36105112, 2022). "In vitro and in vivo experiments further validated the role of CDK2AP1 in tumor growth and metastasis." (PMID 36105112, 2022). "Recently, we have shown the in vivo tumor regression effect of CDK2AP1 with reducing proliferation and increasing apoptotic indices in a xenograft mouse model of head and neck cancer." (PMID 19229340, 2009). "We have extensive lines of evidence demonstrating the function of Cdk2ap1 in cell cycle regulation, apoptosis, and also growth arrest and tumor regression." (PMID 19229340, 2009).
tumor (continued). "We showed that CDK2AP1 genetic ablation triggers a pro-inflammatory secretome encompassing several chemokines and cytokines, thus promoting the recruitment of monocytes into the tumor microenvironment (TME)." (PMID 40112045, 2025). "Furthermore, CDK2AP1 deletion stimulates their differentiation into M2-like macrophages, as validated on tumor microarrays from OSCC patient-derived tumor samples." (PMID 40112045, 2025). "It targets nearly 30 genes, including tumor suppressors such as CDK2AP1, Pdcd4, and BCL2." (PMID 38790924, 2024). "However, more recent studies have revealed a novel role for CDK2AP1 as a core subunit of the Nucleosome Remodeling and Histone Deacetylation complex (NuRD), also likely to be relevant for its tumor-suppressing function." (PMID 37217493, 2023). "By taking advantage of this novel approach specifically designed to study miR/mRNA interactions, we provided additional and more specific evidence of the anti-correlation and spatial segregation between miR-21-5p and CDK2AP1 expression in patient-derived tumor sections." (PMID 37217493, 2023). "Furthermore, proliferation and metastasis assays indicated a critical role of CDK2AP1 in promoting tumor progression." (PMID 36105112, 2022). "Another nine hypermethylated CpG sites can reduce the expression of CDK2AP1, which encodes cyclin-dependent kinase 2 (CDK2), which is important in the reducing of cell proliferation, contributes to cell cycle termination, and is a known tumor suppressor." (PMID 35163587, 2022). "Furthermore, we noticed that the expression of CDK2AP1 was closely related to multiple tumor immune pathway as well as KICH, COAD and UVM checkpoint genes." (PMID 36105112, 2022). "It appears that CDK2AP1 oncogenic overexpression may enhance the ability of tumor cells to evade the immune system." (PMID 36362115, 2022). "The expression level of CDK2AP1 in normal cells was significantly lower than that in tumor cells." (PMID 36105112, 2022). "Furthermore, we use Tumor IMmune Estimation Resource (TIMER) database to study CDK2AP1 expression and Immune Infiltration Levels in HCC." (PMID 36105112, 2022). "This would only be possible if the tumor suppressors or the genes involved in the pathway activated by CDK2AP1 knockdown which causes growth inhibition were normal and not mutated in the cancer cell line of interest." (PMID 25785833, 2015). "Analysis of CDK2AP1 protein expression in these tumor compartments could offer a unique perspective on how the competition between the NuRD and SWI/SNF complexes primes both the tumor cell and its surrounding microenvironment, thus favoring local and systemic dissemination." (PMID 40112045, 2025). "However, when it comes to tumor-associated macrophages with an M2-like profile, the overall differences with CDK2AP1-proficient tumors were not statistically significant, although high infiltration was only observed in CDK2AP1-low/negative tumors." (PMID 40112045, 2025). "In addition to CDK2AP1 and miR-21-5p, the tissue sections were stained with the 34BE12 antibody (Ventana) that recognizes several cytokeratins (i.e., CK-1, -5, -10, and -14) and distinguishes tumor cells from the surrounding stroma." (PMID 37217493, 2023). "Notably, ectopic expression of each candidate miR proved insufficient to recapitulate the complete loss of CDK2AP1 expression observed in SCC lines, suggesting that multiple miRs may collectively contribute to its tumor-specific suppression." (PMID 37217493, 2023). "Therefore, we could propose that CDK2AP1 may influence the tumor immune microenvironment so that patients with high CDK2AP1 levels probably benefit more from immunotherapy." (PMID 36105112, 2022). "FBXW7 was the most recurrently observed F-box protein among K562 hits, paired with many cell cycle related proteins (e.g. CDK2AP1, CDK4, CDKN1A, CKS1B), consistent with the known role of FBXW7 as a tumor suppressor." (PMID 39919746, 2025).